BRCA2 (BRCA2 DNA repair associated)
Diseases named in the same sentence as BRCA2 in open-access papers (continued):
Sharing a sentence is not in itself a finding about the gene and the disease.
breast cancer (continued). "For both BRCA1 and BRCA2 heterozygotes, the strength of the association was greater for ER-positive contralateral breast cancers compared with ER-negative contralateral breast cancers (in the case of BRCA1, even if the ER-negative PRS was used), although most of the confidence intervals overlapped." (PMID 34113011, 2021). "Though this study reported that central nervous system (CNS) metastases were observed at comparable frequencies in both BRCA1- and BRCA2-mutation carriers, when adjusting for breast cancer subtypes, a significant association with CNS metastases was primarily observed in BRCA2 mutation carriers." (PMID 35008272, 2021). "The report stated that receiving diagnostic radiation before the age of 30 years old is associated with the increased risk of breast cancer in BRCA1 or BRCA2 carriers, and the dose level is much lower than the increased risk in other groups exposed to radiation." (PMID 33932123, 2021). "Besides the BRCA1 and BRCA2, mutations in other rare and highly penetrant genes are linked with increased risk of breast cancer development." (PMID 33540843, 2021). "However, many of the BRCA2 mutations found in breast cancer patients and their families are single amino acid substitutions, sometimes unique, and their relevance in cancer risk remains difficult to assess." (PMID 34359619, 2021). "Moreover, the early identification of women who carry pathogenic or likely pathogenic germline variants in BRCA1 or BRCA2 genes will allow the setup of an appropriate diagnostic-therapeutic path to improve the overall survival rate of breast cancer patients." (PMID 34717758, 2021). "A POLQ germline variant of unknown significance, as in the presented family, has already been reported in non-BRCA1/BRCA2-mutated breast cancer families." (PMID 34357098, 2021). "Therefore, physicians can evaluate VUS variant with given risk score 87 patients with pathogenic, 23 with likely pathogenic, 128 VUS, 29 likely benign and 1 benign BRCA1 and BRCA2 gene variants together with 14 other clinical breast cancer risk factors." (PMID 34828379, 2021). "The reason for this observation is unclear, however BRCA2 gene mutation carriers are at a reduced overall breast cancer risk than BRCA1 gene mutation carriers (both alone and in combination with high MD), as shown in data generated from the Tyrer-Cuzik risk assessment calculator." (PMID 34209669, 2021). "His mother with breast cancer and his son were found to have the same BRCA2 mutation." (PMID 34425813, 2021). "According to clinical guidelines, the occurrence of very early-onset breast cancer (VEO-BC) (diagnosed ≤ age 30 years) or VEO ovarian cancer (VEO-OC) (diagnosed ≤ age 40 years) in families with BRCA1 or BRCA2 mutation (BRCAm) prompts advancing the age of risk-reducing strategies in relatives." (PMID 34356116, 2021). "Thus, single nucleotide polymorphisms (SNPs) in the vincinity of the human BRCA2 gene seem to disturb the expression levels of BRCA2 mRNA and increase the breast cancer risk." (PMID 32005245, 2020). "Women with a BRCA1 and BRCA2 mutation and other women with a family history of breast cancer risk may choose to undergo bilateral prophylactic mastectomy." (PMID 32471217, 2020). "BRCA2 mutation carriers may be more sensitive to ovarian hormones than other breast cancer patients." (PMID 32939053, 2020). "Women with BRCA1/BRCA2 mutations had very high risk to develop breast cancer." (PMID 32802855, 2020).
breast cancer (continued). "Breast cancers with loss-of-function mutations in BRCA1 or BRCA2 genes are deficient in the HR (Homologous Recombination) pathway that manages the repair of DNA DSBs (Double Strand Breaks); hence, they are exquisitely sensitive to poly(ADP ribose) polymerase (PARP) inhibitors." (PMID 32903519, 2020). "Also, she carries a BRCA2 mutation and only had unilateral mastectomy, making her at high risk for recurrent or new breast cancer." (PMID 31359344, 2020). "Thus, identification of novel pathogenic germline BRCA2 variants in familial Chinese breast cancers is necessary." (PMID 31782247, 2020). "Developing cancer is not a certainty; risk-reducing salpingo-oophorectomy and antiestrogen therapy may reduce breast cancer incidence, particularly for BRCA2 mutation carriers." (PMID 33238387, 2020). "The study included 258 BRCA1 and 108 BRCA2 mutation carriers with a history of breast cancer." (PMID 32140806, 2020). "Furthermore, evidence of significant hereditary predisposition was found in this cohort (FH of breast cancer, BRCA2 mutations and NBPN, in 20.3%, 32.4%, and 15.5% of cases, respectively) which is line with published literature." (PMID 32295201, 2020). "BRCA1 and BRCA2 are two major genes associated with a lifetime risk of 50%–80% of breast cancer." (PMID 32959997, 2020). "The observations that BPM was associated with lower mortality rates than surveillance for BRCA1 and similar breast cancer-specific survival for BRCA2, underscore the importance of counseling BRCA1/2 mutation carriers on their choice between breast surveillance and BPM." (PMID 31832891, 2020). "The demonstration of increased risks for breast cancer and pancreatic cancer could suggest that genetic variants in BRCA2 may explain some FCCTX families." (PMID 32321466, 2020). "The homologous recombination deficiency (HRD) score was developed using whole-genome copy number data derived from arrays as a way to infer deficiency in the homologous recombination DNA damage repair pathway (in particular BRCA1 or BRCA2 deficiency) in breast cancer samples." (PMID 32818150, 2020). "Morphological and molecular features of BRCA1 and BRCA2-associated breast cancer." (PMID 33117676, 2020). "Chemoprevention with Tamoxifen may be offered for breast cancer primary prevention of BRCA2 carriers, since 75% of BRCA2-associated breast cancer are ER-positive." (PMID 32481735, 2020). "Women with a BRCA1 or BRCA2 gene mutation have up to an 80% lifetime risk of breast cancer unless their breasts are surgically removed, but many decline or defer surgery and choose screening, hoping that if cancer occurs, it will be detected at a curable stage." (PMID 33238387, 2020). "For example, BRCA1 and BRCA2 are mutated in ∼15% of ovarian cancers and ∼6% of breast cancers." (PMID 33015624, 2020). "Besides BRCA1 and BRCA2, it is extremely important to identify new breast cancer susceptibility genes, for the prevention and treatment of FBCs." (PMID 32300589, 2020). "The RAD52 S346X allele was associated with a reduced risk of developing breast cancer in BRCA2 carriers [per‐allele hazard ratio (HR) = 0.69, 95% confidence interval (CI) 0.56–0.86; P = 0.0008] and to a lesser extent in BRCA1 carriers (per‐allele HR = 0.78, 95% CI 0.64–0.97, P = 0.02)." (PMID 32175645, 2020). "We speculate that our observation that hRAD52 S346X confers both a loss of DSB repair and the protection of BRCA2‐mutation carriers against breast cancer will impact future cancer treatments." (PMID 32175645, 2020). "To validate the increased antitumor effect of irinotecan in olaparib resistant model, we tested the antitumor activity of irinotecan in patient-derived xenograft (PDX) models established from a breast cancer patient with BRCA2 580del4 mutation who acquired resistance to olaparib." (PMID 32028591, 2020).
breast cancer (continued). "Moreover, a genetic analysis has identified a breast cancer‐related, BRCA2 single nucleotide polymorphism associated with plasma lipid levels and CVD, as well as lipid and metabolite deregulation in individuals with BRCA2 mutations." (PMID 32638521, 2020). "BRCA2 is another highly penetrant genes involved in hereditary breast cancer susceptibility." (PMID 33013205, 2020). "BRCA2 mutation carriers have a high lifetime risk of breast cancer." (PMID 32939053, 2020). "In addition, BRCA2 c.8187G>T repeated in three cases of our discovery stage was also associated with moderate/low risk of breast cancer in a total of 164 cases and 128 controls from a combined study containing nine studies of Asian ancestry." (PMID 32879886, 2020). "Thus, genetic counselling and long‐term follow‐up should be provided for this family of breast cancer patients as well as carriers carrying a germline variant of BRCA2: c.7007G>T (p.R2336L)." (PMID 31782247, 2020). "Interestingly, heterozygous mutations in FA genes, i.e., BRCA1/FANCS and BRCA2/FANCD1, confer an increased risk of cancer occurrence, especially breast cancer." (PMID 32300589, 2020). "Recently, the EMBRACA and the OlympiaD trials have demonstrated that PARP inhibitor treatment using olaparib or talazoparib improves progression-free survival as compared to standard chemotherapy in advanced breast cancer patients that harbor a germline BRCA1 or BRCA2 mutation." (PMID 32934773, 2020). "Women with a BRCA1 or BRCA2 mutation have a strongly elevated risk of developing breast cancer." (PMID 32333294, 2020). "It is still debated whether BRCA1- and BRCA2-deficiency, which causes genomic instability and increased tumor burden, could increase immunosensitivity in breast cancer and predict clinical benefit from immunotherapy." (PMID 32892748, 2020). "Furthermore, BRCA2-c.1310_1313delAAGA is considered as a North African founder mutation since it has been identified in Algerian, Moroccan and Tunisian breast cancer cases." (PMID 33240314, 2020). "The aim of our study is to evaluate, in a larger group of patients, the contribution of germline mutations in BRCA1 and BRCA2 to breast cancer among Jordanian patients with selected high-risk profile as per the National Comprehensive Cancer Network (NCCN) guidelines." (PMID 32733560, 2020). "Additionally, there is also an increased breast cancer risk associated with the BRCA2 [OR 4.86 (95% CI 4.11–5.74)] and PALB2 [OR 5.1 (95% CI 4.06–6.4)] genes." (PMID 33015624, 2020). "Most of the breast cancer cases are sporadic, and in the 10% of the hereditary cancer, BRCA1 and BRCA2 (breast cancer genes 1 and 2) are the best-known susceptibility genes; they are associated with the risk of up to 85% of developing breast cancer in mutation carriers." (PMID 32341648, 2020). "In summary, our study suggests that the prognostic value of BRCA1/BRCA2 germline mutations in breast cancer patients who were preselected for genetic screening and treated with neoadjuvant or adjuvant chemotherapy depends on the molecular subtype with a survival benefit only in women with TNBC." (PMID 32341426, 2020). "Comprehensively, this study shows that the heterozygous variant of BRCA2: c.7007G>T (p.R2336L) might cause breast cancer in this Chinese pedigree (arrow)." (PMID 31782247, 2020). "Interestingly, we found that Chinese breast cancer patients have more frequent mutations in BRCA2 than in BRCA1 which differ from those in Western breast cancer patients." (PMID 32091409, 2020). "In addition to BRCA1/BRCA2, some other germline mutations in high- and moderate-penetrance genes play significant roles in increasing breast cancer risk for mutation carriers." (PMID 33194720, 2020).
breast cancer (continued). "Unsurprisingly, women with inherited pathogenic mutations in BRCA1 or BRCA2 have up to an 85% risk of breast cancer development; hence, risk reduction measures, such as intensive radiological screening, prophylactic surgery, or chemoprevention were suggested for these candidates." (PMID 32300589, 2020). "Moreover, the genomic footprints in BRCA1-mutated breast cancer are distinct from those bearing BRCA2 mutations, implying the involvement of different mutational processes/mechanisms." (PMID 33087072, 2020). "Our findings suggest that known candidate genes like FGFR2, ESR1, VDR, or BRCA2 could be associated with breast cancer in Uruguay and other admixed Latin American populations." (PMID 33126731, 2020). "Moreover, one early study showed that among BRCA1/BRCA2 mutations carriers, physical exercise and healthy weight were associated with delayed age at breast cancer onset." (PMID 32436147, 2020). "In breast cancer, the absolute risk increase in carriers of BRCA1 and BRCA2 pathogenic variants depends on breast cancer polygenic risk scores, which might influence clinical decision-making." (PMID 32423490, 2020). "We report on a breast cancer patient with constitutional somatic mosaicism of a BRCA2 mutation." (PMID 32468491, 2020). "However, we did not detect any clear relevant variant in 23 genes out of 26, indicating that BRCA1 and BRCA2 are probably the most commonly mutated genes associated with breast cancer predisposition in African women." (PMID 32959997, 2020). "Additionally, they also report the first loss of heterozygosity in canine BRCA2, identified from a canine mammary tumor." (PMID 32005245, 2020). "Of those, 597 BRCA1 and 249 BRCA2 mutation carriers were diagnosed with breast cancer." (PMID 32140806, 2020). "Therefore genetic testing for BRCA1 mutations along with BRCA2 is highly crucial in order to streamline early detection and hence reduce mortality of breast cancer." (PMID 32063924, 2020). "More recently, data had shown that specific breast cancer treatment may be informed by the BRCA1 or BRCA2 mutation status." (PMID 32733560, 2020). "There is evidence that canine BRCA2 gene alterations are associated with mammary tumors." (PMID 32005245, 2020). "Therefore, fertility protection and fertility treatment of healthy carriers of mutations in BRCA1 and BRCA2 as well as of carriers after breast cancer therapy are gaining importance." (PMID 32719921, 2020). "Their study further suggests that the translocation efficiency of BRCA2 may be associated with mammary tumor morbidity in dogs, because the morbidity rate of dogs was higher with AAA insertion than with AAA deletion." (PMID 32005245, 2020). "The Norwegian group was limited to women diagnosed while under surveillance for breast cancer because of BRCA2 mutations (prospective cases), which might explain why the Norwegian patients were, for the most part, diagnosed with early-stage cancers." (PMID 32939053, 2020). "Some BRCA1 and BRCA2 mutations that are inherited increase breast cancer risk in women." (PMID 32824813, 2020). "Accordingly, we investigated the effects on DSB repair in budding yeast of two HsRAD52 variants identified in African-American women with breast cancer, HsRAD52-G59R and HsRAD52-S346X; the latter recently reported to attenuate the pathogenicity of BRCA2 mutations in breast cancer." (PMID 33015141, 2020). "Whether the increased risk of breast cancer and colorectal cancer in these families can be explained solely by BRCA2 germline mutations or by polygenetic defects or environmental factors remains to be elucidated." (PMID 32321466, 2020). "There is some evidence to suggest BRCA2 variants may also be more prevalent in breast cancer cases outside of the French-Canadian population." (PMID 32300229, 2020). "Furthermore, the histological grade of BRCA2-mutated breast carcinoma is generally lower than that of BRCA1-mutated breast carcinoma." (PMID 32269964, 2020).
breast cancer (continued). "Notably, all BRCA1-deficient breast cancers with PTEN mutation clustered within the Thigh group whereas the sole BRCA2-deficient breast cancer with PTEN mutation clustered within the Tlow group." (PMID 31022191, 2019). "Second primary breast cancers are more frequent in carriers of BRCA1/BRCA2 mutations and this higher frequency drives early genetic testing to inform surgical decision-making, even though recent studies have questioned the role of BRCA1/BRCA2 mutations in breast cancer survival." (PMID 31491032, 2019). "Similarly, carriers of mutations in BRCA2 have a 40–84% risk for breast cancer and an 11–27% risk for ovarian cancer." (PMID 31341521, 2019). "Lower levels of BRCA1 and BRCA2 found in shift workers may be one of the potential factors related to the higher risk of breast cancer." (PMID 31405066, 2019). "Considering the type of gene altered in relation to the cancer type or the cancer family history of the patient, we observed a high prevalence of BRCA1 and BRCA2 pathogenic variants in both patients with personal and family history of breast cancer (12.6% (97/768) and 8.7% (9/103), respectively)." (PMID 31159747, 2019). "A proportion of breast cancers are attributable to BRCA1 or BRCA2 mutations." (PMID 30689103, 2019). "We report a BRCA2 pathogenic variant in a Senegalese family with hereditary breast cancer." (PMID 31060517, 2019). "Three hundred ninety women with breast cancer and a BRCA2 mutation were included in the analysis." (PMID 30723304, 2019). "Interestingly, the breast cancer susceptibility gene 1 (BRCA1) and breast cancer susceptibility gene 2 (BRCA2) were found to confer increased susceptibility to colon cancer in a patient with breast cancer under the age of 50 years." (PMID 31183268, 2019). "Similarly, the median number of mutations in TCGA BRCA1- and BRCA2-deficient breast cancers being 2.2 and 2.0 fold higher, respectively, compared to BRCA-proficient breast cancers (P = 6.6 x 10−9 and 6.0 x 10−6, respectively)." (PMID 31022191, 2019). "While most cancers with BRCA1 mutation are TNBC, cancers associated with BRCA2 may display all subtypes of breast cancer, with a similar frequency as in sporadic subtypes." (PMID 31336685, 2019). "More research is needed to evaluate the effect of various chemotherapy regimens on survival in women with BRCA2-associated breast cancer, in particular with platinum-based regimens, which have shown preliminary evidence of effectiveness in BRCA1 mutation carriers." (PMID 30723304, 2019). "Future work may be warranted to investigate additional mechanism by which BRCA1- and BRCA2-deficient breast cancers give rise to different immunophenotype." (PMID 31022191, 2019). "In this study, six BRCA2 mutations were detected in Chinese patients with breast cancer." (PMID 30968603, 2019). "Women who inherit a BRCA1 or BRCA2 mutation have an increased risk of breast cancer." (PMID 31407530, 2019). "Women carrying an inherited BRCA1 or BRCA2 mutation experience similar severity, frequency, and timing of hematologic toxicity as women without a germline mutation while receiving modern day chemotherapy and supportive care for localized breast cancer." (PMID 31407530, 2019). "In unselected patients, BRCA1 and BRCA2 mutations are reported in ranges of 0.3%–13% and 0.75–7.41%, respectively, while in high-risk/hereditary/familiar breast cancer patients, mutations in BRCA1 and BRCA2 were reported in 0.9%–16.6% and 0.49%–18.2%, respectively." (PMID 30792813, 2019). "Moreover, he had a 51‐year‐old son with breast cancer history sharing the same mutation, implicating BRCA2 mutations in elevated cancer risk among Japanese males." (PMID 31631483, 2019).